CYP27B1 (cytochrome P450 family 27 subfamily B member 1)
Diseases named in the same sentence as CYP27B1 in open-access papers (continued):
Sharing a sentence is not in itself a finding about the gene and the disease.
bone disorder (2 papers, 2012 to 2020). "For example, Vitamin D – dependent rickets 1A (MIM: 264700) is primarily a bone disorder, but it is caused by a mutation in the gene CYP27B1, which is active in the kidney and participates in the hydroxylation of Vitamin D into its active form, Calcitriol." (PMID 23028288, 2012). "Although all GM rats showed abnormal bone morphology, Cyp27b1-KO rats showed more severe bone disorders than the other GM rats." (PMID 32231239, 2020).
cardiovascular disease (1 paper, 2025). "In the present study, we analyzed the CYP2R1, CYP27A1, and CYP27B1 genetic polymorphisms and their association with anthropometric parameters, concentrations of 25(OH)D2, 25(OH)D3, 3-epi-25(OH)D2, 3-epi-25(OH)D3, and 1,25(OH)2D3, in Polish patients with cardiovascular disease and healthy subjects." (PMID 40427592, 2025).
metabolic disease (1 paper, 2021). A congenital disorder (due to inherited enzyme abnormality) or acquired (due to failure of a metabolically important organ) disorder resulting from an abnormal metabolic process. "Although no studies have shown a relationship between the polymorphisms of CYP24A1, CYP27B1, and NAFLD, these variants have been extensively investigated in other diseases, such as organ-specific autoimmune endocrine diseases, CVD, metabolic diseases, and multiple cancers." (PMID 34484304, 2021).
CYP27B1 also shares sentences with these, for which no sentence is quoted: bacterial infection (2 papers); chronic rhinosinusitis (2); Crohn disease (2); Growth failure (2); Non-alcoholic Fatty Liver Disease (2); Stroke (2); acrodysostosis (1); acute coronary syndrome (1); acute myocardial infarction (1); Addison’s disease (1); adenoma (1); allergic dermatitis (1); allergic rhinitis (1); Allergy (1); amelogenesis imperfecta (1); anemia (1); atrial fibrillation (1); basal cell carcinoma (1); breast carcinoma in situ (1); calcification (1); cervical tumours (1); Cognitive impairment (1); colon adenocarcinoma (1); colorectal adenoma (1); coronary artery calcification (1); DiGeorge syndrome (1); digestive system tumor (1); electrolyte disorder (1); endometrial cancer (1); Fever (1).
A further 40 diseases each share a sentence with CYP27B1 in 1 paper.